CPS1 (carbamoyl-phosphate synthase 1)
Diseases named in the same sentence as CPS1 in open-access papers (continued):
Sharing a sentence is not in itself a finding about the gene and the disease.
atherosclerosis (3 papers, 2016 to 2025). A disease characterized by the build-up of fatty material and calcium deposition in the arterial wall resulting in partial or complete occlusion of the arterial lumen. "A GWAS of betaine levels, a novel risk factor for atherosclerosis, found an association with variation in a SNP in carbamoyl-phosphate synthase 1 (CPS1) [37••]." (PMID 27726072, 2016). "A GWAS study found that CPS1 localized SNP rs715 (T > C) is associated with plasma TMAO level in females, which increases the risks of atherosclerosis." (PMID 35202247, 2022).
bladder tumor (3 papers, 2019 to 2023). "An NF‐κB activation inhibitor, PDTC, was used at 20 μM in bladder tumour cell lines, and the blockade of NF‐κB activation significantly decreased CPS1 expression." (PMID 31565867, 2019). "A biomimetic fusogenic liposomalized nanoporter (FLNP) that is decorated with urea transporter‐B (UT‐B) is first synthesized with protonated chitosan oligosaccharide for bladder tumor‐targeted co‐delivery of urease and small interfering RNA targeting CPS1 (siCPS1)." (PMID 36775865, 2023). "Furthermore, it has been reported that NFKB, a transcription factor that can be activated by TMAO, induced expression of CPS1 in bladder tumor cell lines." (PMID 35202247, 2022).
chronic kidney disease (3 papers, 2011 to 2022). Impairment of the renal function secondary to chronic kidney damage persisting for three or more months. "The newly discovered loci also include variants previously linked to chronic kidney disease (CPS1, SLC6A13), pulmonary hypertension (CPS1), and ischemic stroke (XYLB)." (PMID 26352407, 2015). "Interestingly a meta-analysis of genome-wide association data in 67,093 individuals also of European ancestry identified recently CPS1 to affect creatinine production and secretion in Chronic Kidney Disease (CKD)." (PMID 21852955, 2011). "Although there is past literature linking TMAO to urea cycle, this is the first published work showing that FMO3 and CPS1 may directly interact, implicating a role for FMO3 in chronic kidney disease irrespective of TMAO formation." (PMID 35202247, 2022).
glioma (3 papers, 2013 to 2023). A benign or malignant brain and spinal cord tumor that arises from glial cells (astrocytes, oligodendrocytes, ependymal cells). "Next, our results suggest that CPS1, one of the five key enzymes of the urea cycle might also be aberrant in gliomas." (PMID 24358143, 2013).
Hepatic fibrosis (3 papers, 2022 to 2025). The presence of excessive fibrous connective tissue in the liver. "Our findings are in alignment with this, due to CPS1, the rate-limiting first step enzyme of urea cycle reduces its levels in parallel with the increase of the hepatic fibrosis." (PMID 35232986, 2022). "As a central regulator of hepatic metabolic homeostasis, CPS1 not only mediates ammonia detoxification but also exhibits aberrant expression patterns correlating with chronic hepatitis C virus (HCV) progression and liver fibrosis staging." (PMID 40565327, 2025).
Insulin resistance (3 papers, 2015 to 2022). Increased resistance towards insulin, that is, diminished effectiveness of insulin in reducing blood glucose levels. "A low level of PC synthesis is responsible for the progression of hepatic insulin resistance and NIDDM.An SNP in CPS1 is linked with the development of NIDDM, but this polymorphic gene may be responsible for the advancement of insulin resistance." (PMID 30678306, 2019).
necrotizing enterocolitis (3 papers, 2010 to 2013). Necrotizing enterocolitis (NEC) is a devastating disease that affects mostly the intestine of premature infants. "In agreement, some polymorphisms in the carbamoylphosphate synthetase (Cps1) gene and hypoargininemia predispose premature infants to the development of necrotizing enterocolitis." (PMID 23785515, 2013). "Previous studies demonstrated the association of the CPS1 T1405 polymorphism with neonatal pulmonary hypertension and necrotizing enterocolitis." (PMID 23997965, 2013). "In preterm infants homozygosity for the CPS1 Thr1405 variant (CC genotype) was associated with an increased risk of having necrotizing enterocolitis (NEC)." (PMID 20520828, 2010).
ovarian carcinoma (3 papers, 2021 to 2023). A malignant neoplasm originating from the surface ovarian epithelium. "Only a few studies demonstrated the potential association of CPS1 with tumor resistance, and the role of this mitochondrial protein in ovarian cancer remained completely unknown to date." (PMID 35008510, 2021). "Our study revealed that CPS1 (carbamoyl phosphate synthetase 1) is expressed in the resistant ovarian carcinoma cell line model." (PMID 35008510, 2021). "Treatment with taxanes led to downregulation of CPS1 in resistant in vitro and in vivo ovarian cancer models." (PMID 35008510, 2021). "In conclusion, this study revealed the expression profile of three candidate molecules: ABCC3, CPS1, and TRIP6, previously associated with MDR phenomena, in resistant and sensitive ovarian carcinoma cell lines and EOC patients." (PMID 35008510, 2021). "CPS1 was significantly overexpressed in resistant SKOV-3 ovarian carcinoma cells in comparison to sensitive SKOV-3 cells and its higher gene expression level was also associated with worse survival rates of EOC patients." (PMID 35008510, 2021). "Our findings provide new evidence that ABCC3 and CPS1 may act as mediators of therapy response in ovarian cancer cells." (PMID 35008510, 2021). "CPS1 was significantly upregulated in the resistant type of ovarian cancer cells." (PMID 35008510, 2021). "The present study observed for the first time a significantly decreased expression of CPS1 in the NCI/ADR-RES paclitaxel-resistant ovarian cancer cells in vitro and had the same effect also in the NCI/ADR-RES-xenografted mouse model in vivo after taxane treatment." (PMID 35008510, 2021). "In concordance with results observed in the in vitro model of paclitaxel-resistant ovarian carcinoma cell line NCI/ADR-RES, we observed the highest level to be that of TRIP6 mRNA, followed by ABCC3 and CPS1 transcripts in our set of EOC tumors." (PMID 35008510, 2021). "We estimated and observed changes in mRNA and protein profiles of ABCC3, CPS1, and TRIP6 in resistant and sensitive ovarian cancer cells and after the treatment of resistant ovarian cancer models with paclitaxel and Stony Brook taxanes in vitro and in vivo." (PMID 35008510, 2021). "We measured the mRNA expression level of ABCC3, CPS1, and TRIP6 in NCI/ADR-RES ovarian carcinoma cell line after 48 h cultivation with paclitaxel (3000 nM concentration), or novel generation taxanes SB-T-121605 and SB-T-121606 (300 nM concentration)." (PMID 35008510, 2021). "In NCI/ADR-RES ovarian carcinoma cell line, we observed the highest level of TRIP6 mRNA followed by CPS1 and ABCC3 mRNA." (PMID 35008510, 2021). "The next goal of this study was to assess whether ABCC3, CPS1, and TRIP6 might serve as biomarkers of prognosis, therapeutic response, and survival of ovarian carcinoma patients for improving therapy personalization." (PMID 35008510, 2021). "Nevertheless, it is not known whether deregulation of ABCC3, CPS1 and TRIP6 occurs in different types of paclitaxel-resistant ovarian carcinoma cells or how the deregulation is affected by the action of paclitaxel and novel taxane derivatives." (PMID 35008510, 2021).
alcoholic fatty liver (2 papers, 2020 to 2024). "In line with changes in liver weight, the transplant of Acod1-/- fecal microbiota in wild-type mice also decreased liver steatosis and increased hepatic mRNA levels of Nags, Cps1 and Ass1 urea cycle genes." (PMID 38302438, 2024).
Anxiety (2 papers, 2025). Intense feelings of nervousness, tension, or panic often arise in response to interpersonal stresses. "We had previously found persistently elevated ammonia in mice when developing a gene therapy approach for CPS1 deficiency; those studies also demonstrated the presence of anxiety-like behavior." (PMID 40421838, 2025). "Together, these data suggest the Cps1 compound heterozygote mice have a heightened general anxiety state, rather than specific fear memory." (PMID 40421838, 2025).
deficiencies (2 papers, 2014 to 2023). "Most UCD patients (n = 54; 68.4%) also received arginine + citrulline at least once during follow-up, with the highest use of the combination in patients with OTC deficiency (38/57; 66.7%) or CPS1 deficiency (13/15; 86.7%)." (PMID 37480106, 2023). "Urine concentrations of orotic acid help to distinguish CPS-1 deficiency from OTC deficiency because they are normal or low in CPS-1 deficiency and elevated in OTC deficiency." (PMID 25908985, 2014). "Family consanguinity was reported in 11 patients overall (13.9%; in 2 patients with OTC Deficiency, 4 patients with CPS1 Deficiency, 4 patients with NAGS Deficiency and 1 patient with ORNT1 Deficiency)." (PMID 37480106, 2023). "Plasma citrulline levels are absent or present in trace amounts in CPS-1 deficiency and in low, or even normal, concentrations in late onset of OTC deficiency." (PMID 25908985, 2014).
esophageal cancer (2 papers, 2021 to 2023). A primary or metastatic malignant neoplasm involving the esophagus. "Patients with stage I esophageal cancer had significantly higher expression of CPS1 (p = 0.003), PNP (p = 0.007), SERPINB8 (p = 0.042) and EHD1 (p = 0.046)." (PMID 33828156, 2021).
Fabry disease (2 papers, 2025). Fabry disease (FD) is a progressive, inherited, multisystemic lysosomal storage disease characterized by specific neurological, cutaneous, renal, cardiovascular, cochleo-vestibular and cerebrovascular manifestations. "These included all patients with leukoencephalopathy, progressive, with ovarian failure (LKENP, n = 2), Fabry disease (n = 1), early infantile epileptic encephalopathy 34 (EIEE34, n = 1), and carbamoyl phosphate synthetase I deficiency (CPS 1 deficiency, n = 1)." (PMID 39080972, 2025).
gastric adenocarcinoma (2 papers, 2023). "The expression of CPS1 mRNA was lower in the stomach adenocarcinoma samples with higher copy numbers of the CPS1 gene." (PMID 37047726, 2023). "The CNV of NAGS and CPS1 were similar in stomach adenocarcinoma samples." (PMID 37047726, 2023).
glutaric acidemia type II (2 papers, 2020 to 2021). "In addition, other types of genetic metabolic diseases were also detected, such as hyperhomocysteinemia, MCADD, MMA, propionemia, 3-hydroxy-3-methylglutaric acidemia, ornithine carbamoyltransferase deficiency, H-TYR, CPS1, CPT2, and glutaric acidemia type II." (PMID 34394177, 2021).
glycogen storage diseases (2 papers, 2015 to 2016). "Concerning Group 2, the 10 positive cases included glycogen storage diseases (n = 2), lysosomal storage diseases (n = 5), neurometabolic conditions (n = 2) and a CPS1 deficiency (n = 1)." (PMID 27243974, 2016).
hemochromatosis (2 papers, 2021 to 2022). A disorder of iron metabolism characterized by a triad of HEMOSIDEROSIS; LIVER CIRRHOSIS; and DIABETES MELLITUS. "We did not detect differences of CPS1 expression with respect to alcohol abuse, NASH, HBV or HCV infection, or hemochromatosis, neither in HCC tissue nor surrounding liver tissue (not shown)." (PMID 33670206, 2021).
Hypertension (2 papers, 2022 to 2024). The presence of chronic increased pressure in the systemic arterial system. "Additionally, the combination of CPS1 variants for glycine exhibited significant associations with lower BP levels and risk of hypertension." (PMID 36307799, 2022). "In addition, suggestive effects of glycine on SBP and risk of hypertension were still observed even when all CPS1 variants were removed from the IV, and such findings were in line with another MR study based on six variants for glycine on cardiometabolic diseases when excluding the CPS1 variant." (PMID 36307799, 2022).
liver disease (2 papers, 2015 to 2017). "CPS1 gene expression is closely linked with numerous kinds of liver diseases." (PMID 28272778, 2017).
metabolic syndrome (2 papers, 2015 to 2021). A cluster of metabolic risk factors for CARDIOVASCULAR DISEASES and TYPE 2 DIABETES MELLITUS. "These proteins included several important blood biomarkers like the indicators for myocardial infarction LDHA/LDHB, the coagulation factor F7, the liver injury marker CPS1, the infection marker CRP, the metabolic syndrome marker FABP534 and the inflammatory predictor GSN35." (PMID 34373457, 2021).
N-acetylglutamate synthase deficiency (2 papers, 2025). "While carglumic acid, approved for treatment of N-acetylglutamate synthase deficiency, can be used to treat a subset of CPS1-deficient patients, this is not a broadly applicable therapeutic option as it depends on a CPS1 mutation with residual enzyme activity." (PMID 40083646, 2025).
prostate carcinoma (2 papers, 2022 to 2023). A carcinoma that arises from epithelial cells of the prostate gland. "In addition, The Cancer Genome Atlas (TCGA) has revealed the high expression of the CPS1 gene in a variety of cancer types, including bladder, colon, esophageal, endometrial, lung, and prostate cancers." (PMID 36139498, 2022).
rectal cancer (2 papers, 2019 to 2021). A primary or metastatic malignant neoplasm that affects the rectum. "One study showed that overexpression of CPS1 associates with poor chemoradiotherapy response in rectal cancer." (PMID 31248089, 2019).
Sepsis (2 papers, 2017 to 2018). Sepsis is defined as life-threatening organ dysfunction caused by a dysregulated host response to infection. "In their experiments, the increase of CPS-1 in the plasma took place much faster than that of alanine transaminase (ALT) during CLP-sepsis: peak CPS-1 levels were observed after 24 hours while ALT levels peaked after 48 hours of CLP injection." (PMID 31225438, 2017). "CPS-1 release into the circulation prior to ALT during sepsis has also been confirmed in the LPS model." (PMID 31225438, 2017). "In addition, the rate-limiting step of the urea cycle mediated by carbonyl phosphate synthase 1 (CPS1) requires Adenosine triphosphate (ATP), which is depleted secondary to sepsis-induced cytopathic hypoxia." (PMID 30049989, 2018). "The increase in CPS-1 in circulation during sepsis should not derive from the enzymatic nature of this protein, but rather from its cellular localization: CPS-1 localizes to the mitochondrial matrix space." (PMID 31225438, 2017).
sickle cell disease (2 papers, 2022 to 2025). Sickle cell anemias are chronic hemolytic diseases that may induce three types of acute accidents: severe anemia, severe bacterial infections, and ischemic vasoocclusive accidents (VOA) caused by sickle-shaped red blood cells obstructing small blood vessels and capillaries. "Bantu, Afro-related ethnolinguistic cultural groups, and Latin America have a similar low proportion of pathogenic variants in most of the sickle cell disease-specific genes, except in MY O 7B, CPS1, COL6A3, MTRR, SLC22A5, ABCC1, and RPL3L." (PMID 35812734, 2022). "However, CRISPR-based therapies are now on the horizon for the treatment of debilitating diseases such as sickle cell disease, cancer, and, most recently, a rare condition called carbamoyl phosphate synthase 1 (CPS1) deficiency." (PMID 40565107, 2025).
adenoma (1 paper, 2023). A neoplasm arising from the epithelium. "And finally, SNORD123, CEACAM6, SNORD78, ANXA10, SPINK1, and CPS1 genes can be used as biomarkers for normal-adenoma comparison." (PMID 37565794, 2023).
Alkalosis (1 paper, 2020). Depletion of acid or accumulation base in the body fluids. "Only one CPS1-deficient male (P8) developed a severe respiratory alkalosis at admission." (PMID 32934962, 2020).
alpha 1-antitrypsin deficiency (1 paper, 2022). Alpha-1-antitrypsin deficiency is a hereditary disease that develops in adulthood and is characterized by chronic liver disorders (cirrhosis), respiratory disorders (emphysema), and rarely panniculitis. "For example, alpha-1 antitrypsin (encoded by SERPINA1) and carbamoyl phosphate synthetase I (encoded by CPS1) are involved in human Alpha-1 antitrypsin deficiency and CPS1 deficiency, respectively." (PMID 35866031, 2022).
arginase deficiency (1 paper, 2018). Arginase deficiency is a rare autosomal recessive amino acid metabolism disorder characterized clinically by variable degrees of hyperammonemia, developing from about 3 years of age, and leading to progressive loss of developmental milestones and spasticity in the absence of treatment. "Pathogenic variants were also identified in arginase deficiency (5 cases), CPS1 deficiency (3 cases), two cases of NAGS deficiency, one case each citrin deficiency and LPI." (PMID 30285816, 2018).
biliary cirrhosis (1 paper, 2025). "This latter model, however, was induced with biliary cirrhosis in mature rodents, and the CPS1 gene therapy studies were conducted in adult mice, both with already developed nervous systems." (PMID 40421838, 2025).
cervical cancer (1 paper, 2019). A primary or metastatic malignant neoplasm involving the cervix. "On the other hand, CPS1 overexpression was observed in rectal, lung, and cervical cancers and was correlated with poor prognosis." (PMID 30967136, 2019).
chronic granulomatous disease (1 paper, 2026). Chronic granulomatous disease (CGD) is a rare primary immunodeficiency, mainly affecting phagocytes, which is characterized by an increased susceptibility to severe and recurrent bacterial and fungal infections, along with the development of granulomas. "It covers implemented solutions for several types of cancer, as well as selected hereditary diseases and syndromes, including Huntington's disease, carbamoyl phosphate synthetase 1 (CPS1) deficiency, hemiplegia, epidermolysis bullosa, chronic granulomatous disease, and congenital deafness." (PMID 41827217, 2026).
coenzyme Q10 deficiency (1 paper, 2020). A genetically heterogeneous condition, typically inherited in an autosomal recessive fashion, characterized by coenzyme Q10 deficiency. "In two patients, NeoSeq enabled diagnosis of inborn errors of metabolism: CPS1 deficiency and primary coenzyme Q10 deficiency, allowing the early initiation of ammonia scavenger therapy combined with a protein-restricted diet and coenzyme Q10 supplementation, respectively." (PMID 32718099, 2020).
cyst (1 paper, 2020). A sac-like closed membranous structure that may be empty or contain fluid or amorphous material. "A recent study suggests that CD49a+ ILC1 may develop from NK cells and exhibit this phenotype in the liver of mice infected with the vaccine strain of T. gondii cps1-1 and a different limited cyst forming type II strain Prugniaud." (PMID 32733814, 2020).
cystic fibrosis (1 paper, 2021). Autosomal recessive disorder caused by pathogenic variants in the CFTR gene (cystic fibrosis transmembrane conductance regulator), which encodes a chloride and bicarbonate channel expressed in epithelial cells, and follow the diagnosis criteria. "By contrast, stronger enrichment of disease risk across pathogenic variants was observed for carbamoylphosphate synthase I (CPS1) deficiency (OMIM 237300) and cystic fibrosis for which 23% and 10% of all disease-associated variants accounted for 70% and 78% of disease, respectively." (PMID 34078906, 2021).
depression (1 paper, 2025). "Six potential depression‐related target genes of miR‐511‐3p were identified: CXCR4, LBR, CPS1, VPS13B, COL9A3, and GABRB3." (PMID 41341504, 2025).
developmental arrest (1 paper, 2014). "It seems as if the expression of CPS1, OTC, ASL, NAGS and GLUD1 in dogs with CPSS has come to a developmental arrest which prevented them to normalize after closure of the shunt." (PMID 24945279, 2014).
diabetic nephropathy (1 paper, 2015). "As T1DM is characterized by oxidative stress and inflammation, CPS1 plays a pivotal role in diabetic nephropathy." (PMID 25726699, 2015).